ZNF547 (zinc finger protein 547)
Description:
May be involved in transcriptional regulation.
Synonyms: FLJ31100
Tractability: PROTAC: ubiquitination databases record sites on it.
Gene: Protein-coding gene on chromosome 19 (57,363,477 to 57,379,565, forward strand). Ensembl gene ENSG00000152433.
Subcellular location: Nucleus
Pathways (Reactome):
Gene expression (Transcription): Generic Transcription Pathway; Regulation of endogenous retroelements by KRAB-ZFP proteins
Gene Ontology:
Molecular function: protein binding; DNA-binding transcription factor activity, RNA polymerase II-specific; RNA polymerase II cis-regulatory region sequence-specific DNA binding; double-stranded DNA binding
Biological process: regulation of transcription by RNA polymerase II; regulation of DNA-templated transcription
Cellular component: nucleus
Genetic constraint (gnomAD): Loss-of-function variants: 4 observed, 8.13 expected, observed/expected ratio (o/e) 0.49, 90% interval 0.24 to 1.12. That is too few expected variants to judge how well the gene tolerates losing a copy. Missense variants: 449 observed, 511.31 expected, observed/expected ratio (o/e) 0.88, 90% interval 0.81 to 0.95. Synonymous variants: 166 observed, 176.46 expected, observed/expected ratio (o/e) 0.94, 90% interval 0.83 to 1.07.
Homologues: Orthologues: chimpanzee ZNF547 (99% identical). Paralogues in human: ZNF17 (65% identical), ZNF416 (51% identical), ZNF530 (51% identical), ZNF776 (46% identical), ZNF417 (43% identical), ZNF587 (43% identical), ZNF287 (42% identical), ZNF34 (40% identical), ZNF285 (38% identical), ZNF527 (38% identical), ZKSCAN7 (38% identical), ZNF852 (37% identical), and 38 more.